DCN (decorin)
Diseases named in the same sentence as DCN in open-access papers (continued):
Sharing a sentence is not in itself a finding about the gene and the disease.
tumor (continued). "Although decorin acts as a tumor suppressor and biglycan is regarded as an oncogene, asporin exerts tumor-suppressor function in triple-negative breast cancer but exerts tumor-promotor function in some types of cancer, including breast, pancreatic, colorectal, gastric, and prostate cancer." (PMID 35600399, 2022). "In addition, the proteoglycan decorin was found to be downregulated in the identified tumor matrisome, consistent with its role as a negative regulator of TGF-β signaling." (PMID 35340765, 2022). "In normal gastric tissue, DCN interacts with TGFβ, leading to tumor suppression." (PMID 36358747, 2022). "Moreover, the results showed that the expression levels of LOXL2, PLOD2, MMP14 and SPOCK1 was higher whereas that of DCN was lower in tumor tissues compared with normal tissues." (PMID 36186418, 2022). "DCN that was involved in cell growth and angiogenesis inhibited tumor progression and fibrosis." (PMID 35627183, 2022). "Therefore, decorin is considered a tumor suppressor that affects cell proliferation, apoptosis, adhesion, invasion, and migration in some cancer cells." (PMID 35777025, 2022). "Moreover, decorin increased the adhesion of tumor cells in vitro, and effectively inhibited cell metastasis." (PMID 35777025, 2022). "Based on these and our observations, we speculated that the decreased expression of protein DCN and slight upregulation of mRNA DCN in liver metastases compared to the primary tumour may reflect the regulation at the post-transcription level by ncRNAs." (PMID 35052821, 2022). "Studies showed that decorin could bind to Met on the surface of tumor cells, leading to rapid receptor phosphorylation and degradation in the endosomes, and could also induce mitochondrial autophagy by activating Met." (PMID 36033387, 2022). "DCN exhibits a tumor-suppressive role as a pan-receptor tyrosine kinases inhibitor." (PMID 36358747, 2022). "Decorin (DCN), a member of the small leucine-rich proteoglycan family, is an extracellular matrix protein that regulates multiple cellular processes, such as angiogenesis, autophagy, and tumor growth." (PMID 35420507, 2022). "Current evidence indicates that decorin plays role in tumor cell cycle arrest and cell apoptosis through epidermal growth factor receptor (EGFR) pathway, and decorin also inhibits tumor angiogenesis after formation of a heterodimeric complex with its key receptor Met." (PMID 34386415, 2021). "Taken together, these results demonstrate that T cells from Nf1OPG mice treated with HDM or OVA produce decorin, which impairs the ability of T cells to stimulate microglia, thus interfering with a tumor supportive microenvironment for murine Nf1-optic glioma formation." (PMID 34880260, 2021). "Co-IP assays were performed to assess whether ASPN and DCN could physically interact with TGFβ in GC tumor and normal tissue." (PMID 34379688, 2021). "Reduced expression of DCN in GC tissues reduced availability for interaction with TGFβ and hence, diminished the involvement of DCN in the TGFβ signaling pathway, further endorsing the tumor suppressive role of DCN in GC." (PMID 34379688, 2021). "Moreover, we analyzed public database (GSE5847) and found that DCN mRNA was expressed in both cancer cells and stroma, with higher expression seen in the tumor cells." (PMID 33452400, 2021). "Further characterization of the DCN-expressing tumor cells or stroma cell types, and cell-type-specific knockout of stromal DCN, may be crucial for fully demonstrating the roles of tumor cell or stroma-derived DCN in IBC tumor biology." (PMID 33452400, 2021). "In addition, another SLRP which warranted concomitant attention was decorin (DCN), a putative tumor suppressor gene." (PMID 34379688, 2021). "In addition, DCN was gradually downregulated from normal, to primary tumor tissues and even more so in PVTT tissues." (PMID 34504839, 2021).
tumor (continued). "The plasma level of DCN was increased and negatively correlated with the stromal DCN expression only in the patients with advanced-stage cancer, indicating that an increasing level of circulating DCN might suggest tumor progression." (PMID 34884232, 2021). "DCN is known to bind and antagonize various receptor tyrosine kinases and autocrine factors to inhibit downstream oncogenic signaling, thereby blocking the growth of cancer cells and tumor xenografts." (PMID 33452400, 2021). "Destruction of structural protein COL1A2, and loss of tumour related proteins CRNN and DCN support the speculation that all three are involved in a pathway for TSCC genesis." (PMID 33889206, 2021). "Alternatively, decorin blocks angiogenic growth signals to restrict tumor growth and dissemination." (PMID 34021540, 2021). "DCN acts as a potent suppressor of tumor growth in many solid tumors including breast cancer." (PMID 33452400, 2021). "Understanding the biological functions and effects of CS on DCN as a tumor suppressor and on other PGs that are modified by CS synthases may offer a novel strategy for developing HCC therapeutic agents." (PMID 33809195, 2021). "On the contrary, some proteolgycans, such as decorin and lumican, could act as tumor suppressors by interacting with key proteins and various receptors." (PMID 34571875, 2021). "Along with the in vitro cellular data, we tested whether decorin could reduce tumor invasion and inhibit autophagy and the EMT phenotype in vivo." (PMID 34386415, 2021). "This might be because a lower abundance of DCN facilitates the development of VI, which accelerates tumor recurrence and metastasis." (PMID 34504839, 2021). "Since the stromal expression of DCN exerted protective functions in tumor growth and tumor spreading, the local delivery of DCN could be a potent novel therapy for inhibiting tumor progression and spreading." (PMID 34884232, 2021). "In this study, it was found that DCN expression in tumour tissues was significantly higher than that in normal tissues, but the difference in advanced and early OC was not significant, suggesting that DCN is an oncogene in tumorigenesis, but it has no predictive effect on tumour development." (PMID 32319226, 2020). "Decorin (DCN), a crucial player in physiological angiogenesis, shows an obvious inhibitory function in angiogenesis within the tumor microenvironment; for example, microinvasive carcinoma of the cervix displayed lower DCN expression than premalignant lesions, as evidenced by immunohistochemistry." (PMID 32899940, 2020). "This three-dimensional acellular portion is composed by fibrous proteins (e.g., collagen, fibronectin, laminin, proteoglycans (e.g., decorin, biglycan, and lumican)) and water, and represents a dynamic structure in continuous remodeling, especially during tumor progression." (PMID 32012917, 2020). "Additionally, ectopic expression of or exogenous treatment with DCN inhibits tumor growth in a variety of preclinical models." (PMID 32908231, 2020). "Decorin is also reported to interact with transforming growth factor-β and receptors of tyrosine kinase such as epidermal and insulin-like growth factors, leading to suppression of proliferation of various tumor cell lines, including HCC cell lines." (PMID 32231160, 2020). "However, the liver metastasis of the same tumor often displayed reduced amounts of decorin, and in a greater extent in the more aggressive grade III tumors, and in metastases with replacement growing pattern." (PMID 32824864, 2020). "By inhibiting tumor metastasis, adding exogenetic decorin inhibited the growth of prostate cancer." (PMID 32825245, 2020). "In situ hybridization data localized DCN expression to areas of microvascular proliferation and immunohistochemical studies localized DCN protein expression to the tunica adventitia of blood vessels within the tumor." (PMID 32908231, 2020).
tumor (continued). "In a cohort of 17 patients with prospectively targeted biopsies there was a positive linear correlation between ADCL levels and DCN protein expression between tumors (Pearson R2 = 0.3977; P = 0.0066) and when evaluating different targets within the same tumor (Pearson R2 = 0.3068; P = 0.0139)." (PMID 32908231, 2020). "Decorin, a member of the proteoglycan family, is also known to have anti-tumor roles." (PMID 32984031, 2020). "Decorin also inhibits tumor cell-mediated production of hypoxia-inducible factor-1α (HIF-1α), and c-Met, and concurrently stimulates the rapid production of the antiangiogenic, angiostatic molecules thrombospondin-1 and tissue inhibitor of metalloproteinases 3 (TIMP3)." (PMID 32489466, 2020). "Notably, systemic delivery of recombinant DCN core protein in a prostate-specific Pten-/- mouse cancer model can slow tumor growth and progression compared to a saline control." (PMID 32553107, 2020). "Moreover, when applied as a therapeutic agent, decorin effectively inhibited tumor formation, progression, angiogenesis, and metastasis in a multitude of experimental models." (PMID 32824864, 2020). "Interestingly, biglycan is a homolog of decorin, but seems to have tumor promoting capacities by angiogenesis induction in contrast to decorin." (PMID 32984308, 2020). "Thus, it is conceivable that the production of TGFβ1 by tumor cells is responsible for decorin downregulation in the neighboring fibroblasts." (PMID 32477937, 2020). "Decorin induced apoptosis via activation of caspase-3 in A431 tumor engraftment cells." (PMID 32731559, 2020). "For different tumor status, DCN, GMPPB and PAM expressed differently." (PMID 32489319, 2020). "Overexpression of decorin could restrain angiogenesis mediated by tumor cell by suppressing the production of vascular endothelial growth factor (VEGF)." (PMID 32339204, 2020). "This could be accounted for since the RNA-Seq data were obtained from heterogeneous tumor tissues which likely harbored contaminating DCN-expressing stromal cells." (PMID 32553107, 2020). "Decorin delivery led to enhanced activity of the p38 MAPK/MSK/CREB axis in tumor-bearing livers." (PMID 32824864, 2020). "In the tumor-free livers of sham-inoculated mice, the delivery of human decorin significantly reduced the level of pIGFR but caused no change in pEGFR or pErk1/2." (PMID 32824864, 2020). "Based on these results, we assume that decorin gene delivery has the potential to inhibit the development of HCC indicating that soluble decorin may act as a tumor suppressor." (PMID 32477937, 2020). "Importantly, when used as a therapeutic molecule in cancer models, DCN was able to block tumor progression and metastases." (PMID 32762776, 2020). "Knockdown of DCN partially reverses MEIS-mediated tumor suppression." (PMID 32553107, 2020). "During the early stages, DCN may be involved in the response to dedifferentiation because a low level of decorin is conducive to the growth of various tumor cell lines and to an increased abundance of anti-inflammatory molecules." (PMID 31832023, 2019). "Our current study revealed that DCN mRNA was decreased in OC compared with NOTs, which was consistent with some previous studies, we hypothesized that DCN can act as a tumor suppressor in OC." (PMID 31703725, 2019). "Specifically, utilizing a transforming growth factor –β (TGF-β)/oncogenic microRNA (miR)-21/tumor suppressor programmed cell death protein 4 (PDCD4) axis decorin downregulates the release of IL-10, which is an anti-inflammatory mediator and thus inhibits tumor growth." (PMID 31068944, 2019). "In addition to regulating growth factor bioactivity and matrix organization, decorin has anti-tumor properties in patients with bone metastases." (PMID 31330786, 2019).
tumor (continued). "Performing its function as “a guardian from the matrix”, DCN slows the spread and metastasis of tumour cells by indirectly inducing vascular endothelial cell autophagy; the possible mechanisms include endothelial autophagic complex formation and reduced synthesis of autophagy inhibitors." (PMID 29435195, 2018). "Furthermore, emerging studies have suggested that DCN is a pan-RTK inhibitor that possesses anti-tumour capabilities involved in cell growth, differentiation, survival and metastasis." (PMID 29435195, 2018). "Thus, decorin is a strong tumor suppressor whereas, the expression of lumican needs to be specifically correlated to the tumor type and stage during the disease progression to draw more relevant conclusions." (PMID 29559954, 2018). "Furthermore, by down-regulating the bioactivity of TGF-β1, DCN decreases the abundance of oncogenic microRNA (miR-21), a transcriptional inhibitor of a tumour suppressor named programmed cell death protein 4 (PDCD4), in a TLR2/4 independent manner." (PMID 29435195, 2018). "Therefore, DCN is promising therapeutic agent for a variety of diseases and shows good prospects for clinical applications as an anti-tumour therapy." (PMID 29435195, 2018). "Decorin’s ability to modulate various signal transduction pathways has given it a valid reputation within cancer and several studies have revealed decorin as a tumor repressor which counteracts tumorigenic and angiogenic growth." (PMID 28793886, 2017). "However, both IFN-γ and TNF-α expression was significantly higher in RdB/IL12/DCN-treated tumor tissues." (PMID 28002796, 2017). "Furthermore, three-dimensional (3D) explant cultures derived from the tumour were transduced with Ad-DCN to study the effect of the transduction on the explants." (PMID 28653173, 2017). "Decorin functions as a tumor repressor, inhibiting cancer growth, migration, and angiogenesis via down-regulation of the oncogenes Myc, β-catenin (in a glycogen synthase kinase 3β-independent manner), and hypoxia-inducible factor 1, α subunit (43, 47, 71, –, 74)." (PMID 28174297, 2017). "In addition, we demonstrated that oncolytic Ad-mediated DCN expression enhanced the distribution of oncolytic Ad within tumor tissues, contributing to efficient transgene expression and the antitumor efficacy of RdB/IL12/DCN." (PMID 28002796, 2017). "We hypothesize that degradation of decorin may have biomarker potential in these pathologies as degradation of decorin might inactivate and disrupt its anti-tumor and anti-fibrotic capabilities." (PMID 28793886, 2017). "Furthermore, reduced decorin within the tumor stroma is a poor prognostic factor of invasive breast-, lung- and soft tissue cancers as well as in myeloma." (PMID 28793886, 2017). "A mechanism through which decorin exerts its tumour suppressor role has been proposed, where decorin may act as a natural antagonist of the oncogene insulin-like growth factor receptor I (IGF-IR)." (PMID 29207682, 2017). "However, such an inhibitory effect of DCN on cancer progression is likely to require a relative healthy autophagy status or an appropriate autophagy capacity in tumor cells." (PMID 27398310, 2016). "Notably, high concentrations of condroitin sulfate PG (CSPG), in particular versican and decorin, have been reported in the tumor stroma." (PMID 27809279, 2016).
tumor (continued). "In addition to in vivo gene therapy studies, where DCN has been expressed from within virus-infected cells, in vivo tumor treatment studies with a recombinant DCN core protein have been carried out with considerable success." (PMID 26697491, 2015). "Furthermore, when used as a therapeutic molecule, DCN has been shown to inhibit tumor progression and metastasis in experimental cancer models." (PMID 26697491, 2015). "In addition to influencing the balance of anti- and proangiogenic factors, the antiangiogenic mechanisms of DCN in tumor angiogenesis involve autophagy." (PMID 26697491, 2015). "Nonetheless, this observation may provide a basis for further mechanistic investigation on decorin in the BM stroma of patients with MM, along with other novel agents, to purge the tumor niche and thereby inhibit growth of MCs." (PMID 26379028, 2015). "DCN is capable of suppressing the growth and metastasis of various tumor cell lines." (PMID 25909163, 2015). "We observed significant upregulation of decorin expression, which may play a role in tumor control, as suggested by the inverse correlations observed between decorin expression and the residual tumor cellularity of the surgical specimens." (PMID 26437222, 2015). "Furthermore, when used as a therapeutic molecule, DCN has been shown to inhibit tumor progression and metastases in experimental cancer models." (PMID 26697491, 2015). "To this end, we investigated the involvement of DCN and LUM in GBM and NB CSC-like models, simulating the phenomena of anchorage loss and the detachment of differentiated tumor cells that underlie the EMT process, and their relationship to CSC-like behavior and the cell response to TMZ." (PMID 26230845, 2015). "In terms of cancer, DCN has been shown to have an antiangiogenic effect on tumor angiogenesis." (PMID 26697491, 2015). "The presence of two closely related proteoglycans in the newly formed tumor stroma indicated that the decreased decorin expression was not caused by the delay in proteoglycan deposition in the newly formed connective tissue surrounding the tumor." (PMID 24634138, 2014). "Decorin has also been shown to decrease tumor growth in experiments conducted in a rat model." (PMID 25140302, 2014). "The overexpression of decorin in the stroma of solid tumors counteracts cell growth, indicating that decorin may have a protective role in tumor progression." (PMID 25140302, 2014). "Interestingly, the SLRP decorin has been found to act as a regulator of endothelial cell autophagy which results in the inhibition of angiogenesis and suppression of tumour growth." (PMID 26056582, 2014). "Decorin has been identified as a tumor suppressor in experimental murine systems 19,20." (PMID 24634138, 2014). "Indeed, the expression of decorin, which is abundant in the stroma, can be used as an indicator of tumor progression." (PMID 25140302, 2014). "The presence of two closely related SLRPs in the tumor stroma indicated that the decreased decorin expression was not caused by the delay in proteoglycan deposition in the newly formed connective tissue surrounding the tumor." (PMID 24634138, 2014). "Consistently, decorin suppression in decorin knock-out mice is permissive for tumor development." (PMID 25526025, 2014). "Interestingly, decorin can also regulate tumour angiogenesis by reducing the production of e.g., VEGF." (PMID 26056582, 2014). "Similarly to decorin, osteoglycin was expressed in normal connective tissue and decreased in the tumor stroma." (PMID 24634138, 2014). "Furthermore, decorin-expressing tumor xenografts grow at significantly lower rates and exhibit significantly suppressed neovascularization." (PMID 25400079, 2014). "Other mechanisms whereby decorin contributes to tumour growth will be discussed later on." (PMID 26056582, 2014). "On the other hand, decorin upregulation inhibits tumor growth by antagonizing tumor angiogenesis." (PMID 25400079, 2014).